DIO2 (iodothyronine deiodinase 2)
Diseases named in the same sentence as DIO2 in open-access papers (continued):
Sharing a sentence is not in itself a finding about the gene and the disease.
Graves disease (2 papers, 2011 to 2020). Graves' disease is an autoimmune disorder that leads to overactivity of the thyroid gland (hyperthyroidism).It is caused by an abnormal immune system response that causes the thyroid gland to produce too much thyroid hormones. "Overexpression of the Dio2 gene has been seen in follicular adenoma and Grave ́s disease." (PMID 33382739, 2020).
Hyperglycemia (2 papers, 2019 to 2021). An increased concentration of glucose in the blood. "Targeted knockdown of hypothalamic Dio2 revealed that it did not mediate the chronic GC effects on hyperphagia and hyperglycemia." (PMID 31176677, 2019).
prostate carcinoma (2 papers, 2020 to 2021). A carcinoma that arises from epithelial cells of the prostate gland. "We also observed higher levels of DIO1, DIO2, and SELENOS, and lower levels of SELENOI in all the prostate cancer cell lines." (PMID 32933107, 2020). "In prostate carcinoma cells, SeNP did not significantly affect the expression of the seven studied selenoproteins; a twofold increase in the expression of SELENOT, SELENOK, SELENON, and DIO2 can be noted." (PMID 34360564, 2021).
schizophrenia (2 papers, 2020 to 2024). A major psychotic disorder characterized by abnormalities in the perception or expression of reality. "Our findings indicate a potential link between schizophrenia and variants of DIO2 rs225014." (PMID 38339190, 2024).
albinism (1 paper, 2019). A congenital disorder characterized by partial or complete absence of melanin pigment in the eyes, hair, or skin. "Similarly, type II iodothyronine deiodinase (dio2) is involved in thyroid hormone conversion, and in flounders it is thought that this conversion promotes pigmentation and prevents albinism." (PMID 30995908, 2019).
bacterial sepsis (1 paper, 2021). "Acute inflammation in mice increases muscle Dio2 mRNA expression, while bacterial sepsis decreases Dio2 mRNA expression both in mice and humans." (PMID 33320308, 2021).
bladder cancer (1 paper, 2019). "Interestingly, DIO2 was upregulated following siEX1 knockdown, also shown to be upregulated in prostate and bladder cancer APSCE." (PMID 30742096, 2019).
cardiac hypertrophy (1 paper, 2020). "To probe this notion further, as well as test the physiological relevance of PTU action on Dio2 to attenuate stress-induced cardiac hypertrophy, we evaluated whether PTU can inhibit T4-dependent activation of reporter activity and whether that inhibitory effect of PTU can be rescued by T3." (PMID 32439985, 2020). "To exclude a global effect of PTU on Dio2 as well as on Dio1 activity, we assessed TAC-induced cardiac hypertrophy in 8- to 10-week-old cKO, control littermates (WT), and age-matched αMHC-Cre-expressing control mice (herein termed Cre)." (PMID 32439985, 2020).
Cirrhosis (1 paper, 2023). A chronic disorder of the liver in which liver tissue becomes scarred and is partially replaced by regenerative nodules and fibrotic tissue resulting in loss of liver function. "However, different genotypic distribution was found for DIO2 rs225014 between patients with cirrhosis who have developed primary malignancy of the liver and those without HCC (p = 0.010426)." (PMID 37059745, 2023).
colitis (1 paper, 2021). Inflammation of the colon. "DSS-induced colitis mice showed significantly decreased expressions of PPARα, PGC-1α, and thermogenic genes including ND5, Prdm16, Cidea, Elovl3, Dio2, and UCP1 both in SAT and BAT compared to non-colitis control mice." (PMID 33674694, 2021).
COVID-19 (1 paper, 2025). A disease caused by infection with severe acute respiratory syndrome coronavirus 2. "Among the 5 common DEGs, four were significantly downregulated (ERP27, SYTL5, EXTL1, DIO2) and one was upregulated (STXBP6) in the COVID-19 dataset." (PMID 40660393, 2025).
deafness (1 paper, 2024). An inherited or acquired condition characterized by the complete loss of the ability to hear from one or both ears. "Dio2-deficient mice exhibit deafness and cochlear defects, but the low and transient expression of Dio2 made it difficult to identify the specific cell types expressing Dio2 in the cochlea." (PMID 38015350, 2024).
emphysema (1 paper, 2023). "In order to assess the T3 requirement in the lungs of the elastase-induced COPD model mice, simulating emphysema-dominant COPD, we examined the mRNA expression levels of Dio2, an enzyme that converts T4 into active T3, in the lung tissues." (PMID 38247455, 2023). "In this study, we found that the expression level of Dio2 increased and Ppargc1a decreased in elastase-induced COPD mice (emphysema-dominant COPD model) but not in C57BL/6J-βENaC-Tg mice." (PMID 38247455, 2023).
endometrial cancer (1 paper, 2022). Primary or metastatic malignant neoplasm involving the endometrium (mucous membrane that lines the endometrial cavity). "In the literature review, no analyses were found regarding the relationship between the polymorphisms GPX1 (rs1050450), DIO2 (rs225014) and SEPP1 (rs7579) and the possibility of developing endometrial cancer." (PMID 35205233, 2022). "Our study attempted to determine whether polymorphisms in selected genes important for selenium metabolism, GPX1 (rs1050450), DIO2 (rs225014) and SEPP1 (rs7579), are associated with the risk of developing endometrial cancer." (PMID 35205233, 2022).
euthyroid sick syndrome (1 paper, 2017). Abnormal thyroid function tests, low triiodothyronine with elevated reverse triiodothyronine, in the setting of non-thyroidal illness. "One reaction was identified between Type II 5-deiodinase (DIO2), thereby suggesting that food immune reactivity with buckwheat may potentially impact T4 to T3 thyroid conversion associated with nonthyroidal illness syndrome (NTI), or euthyroid sick syndrome." (PMID 28894619, 2017).
fibrosis (1 paper, 2023). the formation of excess fibrous connective tissue in an organ or tissue in a reparative or reactive process. "In further analysis when the cohort was segregated into those with mild (F0–1) versus advanced fibrosis (F2–4), carriage of DIO2 rs225014 TT and rs225017 AA, and PPARG rs10865710 CC genotypes were associated with a significantly increased risk of advanced fibrosis, independent of age and gender." (PMID 37059745, 2023).
glioblastoma (1 paper, 2024). The most malignant astrocytic tumor (WHO grade IV). "In summary, Dio2 mRNA is a target of MSI1 and the MSI1–D2–T3 pathway is a novel regulatory mechanism of astrocyte proliferation with the potential to regulate the pathogenesis of human glioblastoma." (PMID 38879014, 2024).
idiopathic pulmonary fibrosis (1 paper, 2023). Idiopathic pulmonary fibrosis (IPF) is a nonneoplastic pulmonary disease that is characterized by the formation of scar tissue within the lungs in the absence of any known cause. "Recently, the increased expression of Dio2 and decreased expression of Ppargc1a (peroxisome proliferator-activated receptor gamma coactivator 1-alpha), a master regulator of mitochondrial biogenesis, had been shown in a mouse model of refractory lung disease, idiopathic pulmonary fibrosis (IPF)." (PMID 38247455, 2023).
lung fibrosis (1 paper, 2023). "In this context, iodothyronine deiodinase 2 (DIO2), the enzyme which converts and activates thyroxine (T4) to 3,3′,5-triiodothyronine (T3) was elevated in patients with lung fibrosis, and Dio2 knockout mice suffered from a more severe disease." (PMID 37686465, 2023).
Miscarriage (1 paper, 2023). A pregnancy that ends at a stage in which the fetus is incapable of surviving on its own, defined as the spontaneous loss of a fetus before the 22th week of pregnancy. "The expressions of Dio2 and Dio3 were significantly down-regulated in villi of the miscarriage group compared to the ETP group." (PMID 37968664, 2023). "Additionally, the western blot results demonstrated that the expression of Dio2 was downregulated in the placental villi of miscarriage patients." (PMID 37968664, 2023). "In addition, Dio2 and Dio3 presented lower expression at the mRNA level in the villi of miscarriage cases." (PMID 37968664, 2023). "In miscarriage group, the gene expression of Dio2, Dio3, TTR and THRα, but not THRβ, MCT8 and OATP1A1, were downregulated." (PMID 37968664, 2023).
osteoarthritis (1 paper, 2021). A noninflammatory degenerative joint disease occurring chiefly in older persons, characterized by degeneration of the articular cartilage, hypertrophy of bone at the margins and changes in the synovial membrane. "Finally, we phenotype previously generated mutant mice with an osteoarthritis-associated polymorphism in the Dio2 gene by CRISPR/Cas9 genome editing and demonstrate a protective role in disease onset with public health implications." (PMID 33473114, 2021). "Finally, we phenotype previously generated CRISPR/Cas9 mutant mice with a Thr92Ala polymorphism in the Dio2 gene that is orthologous to the human variant associated with osteoarthritis susceptibility." (PMID 33473114, 2021). "Nevertheless, DIO2 has not been associated with osteoarthritis in GWAS, and the role of the DIO2 rs225014 polymorphism remains controversial, attracting much debate even beyond the osteoarthritis field." (PMID 33473114, 2021). "By contrast, Dio2Ala92 mutants had no signs of osteoarthritis, indicating a protective role for the Ala92 polymorphism and providing the first functional evidence of a role for this candidate DIO2 polymorphism in vivo." (PMID 33473114, 2021).
pterygium (1 paper, 2025). A wedge-shaped fibrovascular lesion arising from the bulbar conjunctiva and extending to the cornea. "A similar tendency was observed in pterygium tissues versus normal controls, with a significant decrease in the level of four genes (ERP27, SYTL5, EXTL1, DIO2) and an increment of gene STXBP6." (PMID 40660393, 2025).
retinal degeneration (1 paper, 2023). Degeneration of the retina. "Previous studies have shown that degenerating retinas in mouse models of retinal degeneration show increased expression of TH receptor/Thrb2 and iodothyronine deiodinases/Dio2, suggesting that TH signaling activity is likely locally elevated in degenerating retinas." (PMID 37596046, 2023).
Sepsis (1 paper, 2017). Sepsis is defined as life-threatening organ dysfunction caused by a dysregulated host response to infection. "Our main finding indicates that, during fasting, Dio2 up-regulation in PVN/ARC nuclei seems to be an adaptive mechanism involved in the HPT-axis impairment, while in CLP-induced sepsis this impairment is probably associated with inflammatory mediators and independent of T3 uptake and action." (PMID 29118715, 2017). "Herein, we aimed to evaluate the central and peripheral expression of genes involved in the transport (MCT8/Slc16a2 and MCT10/Slc16a10), metabolism (Dio1, Dio2, and Dio3) and action (Thra and Thrb) of TH during NTIS induced by fasting or sepsis." (PMID 29118715, 2017). "Dio2 expression did not change in the total hypothalamus of CLP-induced sepsis mice, compared to control group." (PMID 29118715, 2017). "In attempt to investigate the dramatic reduction in Tshb expression, and since Dio2 expression did not change in the total hypothalamus of CLP-induced sepsis mice, we decided to perform a more thorough analysis of Dio2 expression in PVN and ARC nuclei only during fasting." (PMID 29118715, 2017).
vascular dementia (1 paper, 2025). A degenerative vascular disorder affecting the brain. "Loci CAMK2D and ATPase phospholipid transporting 8A2 (ATP8A2) were also replicated with these two exposures for vascular dementia, whereas loci iodothyronine deiodinase 2 (DIO2) and PSMG1 were replicated with oily fish intake and ω-3 concentrations." (PMID 40949174, 2025).
tumor (5 papers, 2021 to 2024). "The results showed that CAFs in P-LNs were associated with the high expression of NFIB, IGLC2, IGHG4, C7, and CCL19, while CAFs in tumor 3 had high expression of DIO2, LGALS1, WNT5A, NEAT1, and MMP11 in the tumor." (PMID 36569924, 2022). "Key differentially expressed genes included PTGS2 (pro/antitumor), FOSL1, TNFRSF9, IL1B, DIO2, and PHLDA1 (antitumor), along with under-expressed genes with pro-tumor effects that may inhibit proliferation." (PMID 39409923, 2024).
cancer (3 papers, 2012 to 2025). A tumor composed of atypical neoplastic, often pleomorphic cells that invade other tissues. "Moreover, gene expression profiling in normal versus malignant thyroid tissues demonstrated a downregulation of DIO1 and DIO2, which could be linked to Pax8 loss during cancer progression." (PMID 22531031, 2012). "Strikingly, DIO2 – which is expressed in normal thyroid tissue – was significantly upregulated in ATC vs PTC, suggesting that its expression in the context of ATC plays a different role than in normal thyroid cells, likely necessary for cancer progression." (PMID 36877008, 2023).
retinopathy (1 paper, 2020). "Our data suggest that aberrant Dio2/TH signaling is an important factor in the pathophysiology of the visual dysfunction observed in the oxygen-induced retinopathy model of ROP." (PMID 33237298, 2020).
DIO2 also shares sentences with these, for which no sentence is quoted: Alzheimer disease (2 papers); autism (2); Hashimoto’s disease (2); heart failure (2); Kashin-Beck disease (2); metabolic disease (2); metabolic syndrome (2); thyroid cancer (2); vitamin D deficiency (2); adenomyosis (1); Arthritis (1); atherosclerosis (1); behavioral disorders (1); bipolar disorder (1); cardiovascular disease (1); chronic hepatitis b (1); congenital hypothyroidism (1); dentatorubral-pallidoluysian atrophy (1); dilated cardiomyopathy (1); endocrine system disorder (1); follicular adenoma (1); Glucose intolerance (1); hand osteoarthritis (1); Leber congenital amaurosis (1); lung injury (1); mood disorder (1); neuroblastoma (1); neurological disorders (1); Parkinson disease (1); prediabetes (1).
A further 2 diseases each share a sentence with DIO2 in 1 paper.